CXCR4 (C-X-C motif chemokine receptor 4)
Diseases named in the same sentence as CXCR4 in open-access papers (continued):
Sharing a sentence is not in itself a finding about the gene and the disease.
tumor (continued). "In addition, both preclinical and clinal trials indicated that targeting CXCR2 and CXCR4 increased the efficacy of immunotherapy by reducing tumor neutrophil infiltration and promoting adaptive immune responses." (PMID 35158948, 2022). "In addition, CXCL12 and CXCR4 are involved in antigen recognition by T and B cells and in shaping the tumor microenvironment (TME), mainly towards dampening immune responses." (PMID 35565443, 2022). "Therefore, while this antagonist has proved effective in controlling tumor progression in various cancers, these observations suggest caution in its use to understand the respective roles of CXCR4 and CXCR7 as mediators of the biological effects of CXCL12." (PMID 35406582, 2022). "Thus, combining plerixafore (AMD3100; CXCR4 inhibitor) with immune checkpoint inhibitor anti-PDL1 antibody showed decreased tumor volume." (PMID 35638450, 2022). "The finding that much of the circulating CD3+CD8+ subset was positive for the chemokine receptor CXCR4 in patients with long DMFS is in line with data from a mouse model, in which CXCR4 expression bestowed the cytotoxic T cells the function to reach the tumour target tissue." (PMID 34961902, 2022). "The dual blood supply in the liver, the anatomy of sinusoidal spaces, and the high CXCL12 expressing sinusoidal endothelial cells together facilitates circling tumor cells with CXCR4 expression adhere and extravasate into the liver parenchyma and establish distant organ metastases." (PMID 35145271, 2022). "The proliferation and invasion of oral cancer is bolstered by tumor-infiltrating pDCs through the activation of the TNF-α/NF-κB/CXCR-4 pathway, which may serve as a potential immunological target for the treatment of OSCCs in the future." (PMID 35740551, 2022). "Similarly, stromal cell-derived factor (SDF)-1α and PDGF-B released by tumor cells bind CXCR4 and PDGFR-β on MSCs, respectively, resulting in differentiation into pericytes, leading to vasculogenesis and tumor recurrence." (PMID 35842634, 2022). "Angiogenesis mediated by SDF-1 binding to CXCR4 promotes tumor growth." (PMID 36131788, 2022). "This improved tumor-targeting efficiency might be attributed to the dual CXCR4 and integrin αvβ3 binding ability of 68Ga-yG5-RGD in BxPC3 tumors." (PMID 36145541, 2022). "In cancer, CXCR4 overexpression contributes to tumor growth, metastatic dissemination, and relapse." (PMID 35715791, 2022). "CXCR4 activates tumor metastases and its ligand CXCL12 is substantially generated." (PMID 36211359, 2022). "Also, CXCR4 inhibition in combination with anti-CTLA4 treatment was superior over each treatment alone in reducing tumor growth in a pancreatic tumor model." (PMID 36102918, 2022). "To determine whether the inhibitory effect of BsNb PX4 on tumour cells correlated with the expression of CXCR4, we examined the proliferation of four different cancer cell lines using CCK-8 assays." (PMID 36284271, 2022). "Furthermore, the CXCR4/CXCL12 axis is reported to be involved in promoting tumor invasion and metastasis, and downregulation of CXCR4 is of great significance in inhibiting cancer metastasis." (PMID 35637953, 2022). "TEMs express the chemokine receptor CXCR4 and can be attracted into tumours by CXCL12." (PMID 36497114, 2022). "Except CXCR4, all hub genes expressed differently between tumor and normal samples." (PMID 35768705, 2022). "NFATc4 could promote tumor formation through CXCR4 expression up-regulation whereas NFATc4 inhibited cell proliferation by down-regulating MYC during cisplatin resistance-associated quiescence." (PMID 35698138, 2022). "In addition, HSCs, together with liver sinusoidal endothelial cells, are one of the principal sources of CXCL12 secretion in the liver, where they mediate not only the recruitment of CXCR4-expressing tumor cells, but also of CXCR4-expressing immune cells." (PMID 35406582, 2022).
tumor (continued). "Even though the sample size was very small, they demonstrated the ability of 68Ga-Pentixafor PET/CT to detect all schwannomas with sufficient tumour to background and tumour to blood pool ratios that matched with membranous CXCR4 expression as assessed by immunohistochemistry." (PMID 36140541, 2022). "CXCR4 notably improves the detection limit of current imaging methodologies of late-stage metastases (4 out 4, tumor diameter 1–2 cm) to early-stage metastases (stage 2, tumor diameter 0.1 mm)." (PMID 35145271, 2022). "A possible explanation for this observation may be that DOX increases CXCR4 expression in vivo and in vitro in different tumor models." (PMID 35805197, 2022). "In addition, the interaction between CXCL12 and its receptor CXCR4 has generated widespread interest with regard to tumor progression." (PMID 35893797, 2022). "Interestingly, in subcutaneous EC models, CXCR4 expression increases EC cell engraftment and tumor growth rate." (PMID 35884987, 2022). "That discrepancy might be due to the high heterogeneity of SST and CXCR4 expression among individual tumours, which was visible in the whole-block tumour samples." (PMID 35799158, 2022). "We then checked if EGFR and CXCR4 in sEVs derived from serum could act as tumor detection biomarkers for NSCLC." (PMID 35269297, 2022). "Therefore, we first evaluated the association of CXCL12, CXCR4, and FAPα mRNA expression with immune cell infiltration and procancer pathways in LARC using the Tumor IMmune Estimation Resource (TIMER) database and GSEA." (PMID 34976180, 2022). "Furthermore, myofibroblasts sequester CD8+ T cells to prevent them from attacking tumor cells via the CXCL12/CXCR4 signaling pathway." (PMID 35972800, 2022). "In addition, CXCR4 has been identified as a key chemokine receptor which attracts pro-tumoural myeloid-derived suppressor cells (MDSC) to the tumour site." (PMID 35205725, 2022). "Additionally, ligand-induced endocytosis of CXCR4 and its internal sequestration are also well known in leukocytes, stem cells, and tumor cells." (PMID 35797269, 2022). "Thus, CXCR4+ SW1417 cells were injected into Swiss nude mice to generate a subcutaneous tumor model." (PMID 35532120, 2022). "The missing tumor sink effect could also have an impact on scan interpretation, e.g., if CXCR4-expressing lesions are close to normal organs, such as spleen or bone marrow." (PMID 35312939, 2022). "Additionally, we have reported on the use of imaging the tumor microenvironment using CXCR4-targeted PET/CT imaging in EAC." (PMID 34882260, 2022). "However, the tumor volume of mice in the CXCR4/SKOV3 groups treated with PTX did not change compared with mice in the Scramble/SKOV3 group." (PMID 35681259, 2022). "CXCR4 also contributed to neutrophil recruitment in the tumor metastasis." (PMID 35585567, 2022). "Administered activity of [177Lu]Lu-/[90Y]Y-PentixaTher or drug doses of “cold” CXCR4 antagonists could then be increased in patients with high tumor burden, maximizing efficacy in sites of disease and reducing off-target effects in unaffected organs." (PMID 35312939, 2022). "Finally, plerixafor can induce a better immune response against the tumor through the suppression of Treg cells and the regulation of T cell activity, and recent studies have reported that CXCR4 inhibition enhances the response to immunotherapy." (PMID 36613922, 2022). "Therefore, targeting CXCR4 slows tumour growth, reduces angiogenesis as well as the expression of VEGF and increases the sensitivity of malignancies to chemotherapy, leading to apoptosis." (PMID 36140541, 2022). "Recently, a PET tracer targeting the chemokine C-X-C motif receptor 4 (68Ga-CXCR4) has been developed driven by the knowledge that the CXCR4/SDF1 (stromal derived factor 1) axis may play an important role in various tumours and especially in MM." (PMID 34363522, 2022).
tumor (continued). "Studies found that targeting CXCL12/CXCR4 signaling by an OV expressing CXCR4 antagonist effectively disrupted the tumor vasculature, induced ICD of cancer cells, reversed immunosuppressive TME and improved antitumor immunity, including inhibition of cancer metastasis." (PMID 36221123, 2022). "CXCR4 hyperactivation is closely related to changes in the tumour microenvironment." (PMID 35563449, 2022). "Indeed, the CXCR4-mediated proliferation and metastasis of tumor cells was shown to be regulated by CXCR7 through its scavenging of CXCL12." (PMID 35406450, 2022). "The movement of cancer cells toward CXCL12 in metastatic sites is determined by the gain of CXCR4 expression and the loss of CXCL12 on the primary tumor at the same time, enabling movement of tumor cells, along with the CXCL12 gradient, toward the metastatic niche." (PMID 35203510, 2022). "The developed CXCR4+ SC EC tumor model could be used to evaluate the antitumor activity of novel CXCR4-targeted drugs, since SC tumor models are widely used in preclinical drug development for EC therapy." (PMID 35884987, 2022). "In addition, CGN expression was negatively associated with the tumor-promoting factors BIRC5 and CXCR4." (PMID 35223987, 2022). "CXCR4 is a specific chemokine receptor for stromal cell‐derived factor‐1 that is expressed on cancer cells and many other cells in the tumor microenvironment, and has many important functions including promoting tumor progression and metastasis and facilitating angiogenesis." (PMID 35505641, 2022). "Therefore, we generated the Hazard Cox regression considering the dichotomized (p)CXCR4 tumor as well as TIC expression in primary and recurrent cancer biopsies." (PMID 35397601, 2022). "In addition, inhibition of the interaction between CXCL12 and CXCR4 promoted T cell accumulation in central tumor areas and increased the effect of immune checkpoint blockade, suggesting that CXCL12 promotes spatial elimination of T cells." (PMID 36010986, 2022). "We first examined the expression status of RON and CXCR4 in tumor sections." (PMID 36103228, 2022). "First, for miR-494-3p, the modulation of CXCR4 mediated by the ectopic expression of miR-494-3p can suppress the proliferation and migration of the cells of SS, which means that miR-494-3p functioned as a tumor suppressor in SS." (PMID 36003502, 2022). "These evidences suggest that in the HNSCC TME, hypoxia might promote the migration of pDCs into tumor tissues through the HIF‐1α/SDF‐1/CXCR4 pathway." (PMID 34964283, 2022). "CTCE‐9908 (CXCR‐4 antagonist) is a 17‐amino acid sequenced peptide consisting of a dimer of eight amino acid N‐terminal sequences, that has shown to inhibit adhesion and growth of tumour cells." (PMID 36398426, 2022). "Furthermore, in many kinds of cancers, the C-X-C motif chemokine ligand 12 (CXCL12)/CXCR4 axis plays a role in tumor formation and metastatic dissemination." (PMID 36003502, 2022). "Moreover, CXCR4 overexpression, in HNSCC and other neoplasias, also associates with resistance, relapse and metastatic potential." (PMID 35120582, 2022). "However, a phase II study with the CXCR4 antagonist BL-8040 (motixafortide) showed that BL-8040 increased the tumor infiltration of CD8+ T cells and decreased MDSCs and Tregs (NCT02826486)." (PMID 36010986, 2022). "Exploratory in vitro studies in the context of tumor immunotherapy have shown that CX-01 may also interfere with the CXCL12/CXCR4 axis." (PMID 35053249, 2022). "Interestingly, among patients with radical resection (R0), high tumor CXCR4 clustered patients with worse RFS, high CXCL12 identified poor prognostic patients for both RFS and CSS, while stromal lymphocytic-monocytic PD-L1 associated with improved RFS and CSS." (PMID 36359736, 2022).
tumor (continued). "They discovered that CXCR4 inhibition with AMD3100 attenuated CXCL12 release from cancer-associated fibroblasts (CAFs), and concomitant treatment with an anti-PD-L1 antibody reactivated tumor immune recognition and eradicated PDAC in a murine model." (PMID 35797269, 2022). "This aspect was also underlined by the only article targeting CXCR4, which suggested that the associated use of [18F]FDG and [68Ga]pentixafor could provide complementary information on tumor biology." (PMID 35884548, 2022). "Studies also showed the role of CXCR4 in crosstalk between tumor cells and their microenvironment." (PMID 35397601, 2022). "Thus, elevated expression of CXCR4 by carcinoma cells favours the primary tumour in murine xenograft models, whereas deletion of this marker in breast carcinoma cells inhibits tumour growth." (PMID 36555218, 2022). "In addition, the transcriptomic profiles showed that both the NK-FCGR3A-CCL3 and NK-FCGR3A-S100A8 in BM with low tumor infiltration expressed high level of CXCR4 compared to the corresponding sub-clusters in HD and high infiltration group." (PMID 36532059, 2022). "Moreover, NK cells co-expressed with the CXCR4 increased the infiltration of NK cells and enhanced the killing effect of tumor cells." (PMID 35388021, 2022). "In clinical practice, this would theoretically mean that if a newly discovered tumor expresses CXCR4, [68Ga]Ga-Pentixafor PET could be complementary to tumor imaging, and facilitating surgical and radiotherapy planning." (PMID 33550492, 2022). "In murine solid tumor models, including ovarian cancer, glioblastoma, and pancreatic cancer, the CXCR4 antagonist AMD3100 has been shown to decrease tumor angiogenesis and revascularization, reduce lung metastasis, and induce infiltration of CD8+ T cells into tumors." (PMID 36923305, 2022). "68Ga-Pentixafor has shown promise as an elegant radiotracer to aid in the selection of patients whose tumours demonstrate CXCR4 overexpression and who therefore may benefit from novel therapies targeting CXCR4." (PMID 36140541, 2022). "Increased CXCL12 expression in hypoxic tissues is important for the homing of tumor stem cells in circulating tissues, CAFs secrete CXCL12, attract CXCR4-expressing tumor cells and endothelial progenitor cells, thereby promoting angiogenesis in the liver’s pre-metastatic niche." (PMID 35965504, 2022). "Tumor expressing CXCL12 can also promote pDCs expressing CXCR4 in the tumor microenvironment." (PMID 35884612, 2022). "The SDF‐1/CXCR4 pathway is well known to be involved in tumor progression." (PMID 34964283, 2022). "Several studies have demonstrated that CXCR4 could promote cell proliferation in pulmonary vasculature and some tumor cells via PI3K/Akt and RhoA/ROCK signaling pathway." (PMID 35865003, 2022). "The molecules involved in the interactions between tumor cells and the adjacent fibroblasts may include Wnt/beta-catenin, transforming growth factor beta, and C-X-C chemokine receptor type 4 (CXCR4)." (PMID 35492308, 2022). "Another important study has demonstrated that tumor-infiltrating MDSCs usually are CXCR4 positive and could migrate toward the CXCL12 gradient." (PMID 34980128, 2022). "CXCR4 downregulation or blocking of the CXCR4/CXCL12 signaling pathway inhibits tumor metastasis." (PMID 35910383, 2022). "The CXC chemokine receptor 4 (CXCR4) has become a very promising target for tumor therapies." (PMID 35630915, 2022). "Antagonizing SDF1/Cxcr4 signaling is approved for stem cell mobilization from the bone marrow and is under extensive research in oncology, as it is critical for tumor development, metastasis and tumor cell migration." (PMID 36178806, 2022). "Several studies have demonstrated that the activation of the SDF-1α/CXCR4 axis enhances tumor growth, invasion and gene transcription; and the inhibition of the SDF-1α/CXCR4 signal pathway reverses this phenomenon, contributing to apoptosis, cell cycle arrest, and malignant properties." (PMID 35453553, 2022).
tumor (continued). "Expressions of CXCR4 and integrin αvβ3 in tumor tissues were analyzed by immunohistochemistry." (PMID 36145541, 2022). "Thus, human vimentin reliably identifies all human tumor cells in the studied section of affected organs, including single EC cells infiltrating the tissue (which anti-CXCR4 or H&E cannot) and small or large size metastatic foci." (PMID 35884987, 2022). "Furthermore, the CXCL12/CXCR4 axis is also critical for tumor cell metastasis and drug resistance in cancer therapy." (PMID 35702353, 2022). "The purpose of this study was to determine whether RON regulates the expression of CXCR4, a chemokine receptor that plays a critical role in tumor cell invasion and metastasis." (PMID 36103228, 2022). "CXCR4‐mediated angiogenesis may improve the hypoxia status of the tumor in the pre‐treatment sample and thereby sensitize the cancer cells to radiation." (PMID 35505641, 2022). "In vivo, injections of colonic tumor cells overexpressing miR-9 into the tail vein of mice resulted in fewer lung metastases than with control cells, a similar effect obtained with cells deleted for CXCR4 expression." (PMID 35406582, 2022). "Chemokines and their receptors, principally the chemokine (C-X-C motif) ligand 12 (CXCL12) and its receptor CXCR4, have gained attention for their functional roles as being able to communicate between tumor cells and the tumor microenvironment including immune and vascular cells as also the stroma." (PMID 34445691, 2021). "Methylation patterns also play an important role in CXCR4 expression, the lack of them being associated positively with tumor size, stage, lymph node status, metastasis, and CXCL12 promoter region methylation." (PMID 33530455, 2021). "The results showed that ACE treatment could significantly reduce both the protein and mRNA expression levels of SDF-1 and CXCR4 in tumour tissues." (PMID 34531745, 2021). "As we could not detect tumor cells by tissue staining at this early time point, we used qRT–PCR for Neu which revealed expression in PBS controls that was lower upon CXCR4 inhibition, indicative of less tumor cells in the lung." (PMID 33988305, 2021). "The CXCL12/CXCR4 axis plays a leading role in the CLL cell-tumor microenvironment interactions." (PMID 34207596, 2021). "CXCL12 also plays a role to initiate and promote tumor through CXCL12/CXCR4 axis." (PMID 34168096, 2021). "Hence, treatment of KPC mice (a genetically engineered PDAC mouse model) with a CXCR4 inhibitor promoted T cell recruitment into the tumor, enhancing the efficacy of anti-PD-L1 agents, and drastically reducing PDAC progression." (PMID 34298680, 2021). "Indeed, a study demonstrated that stem cells number in tumor spheroid raised in response to chemotactic signals, specifically increased expression of the SDF1/CXCR4 axis, which induced the recruitment of these cells at the tumor sites." (PMID 34830817, 2021). "Indeed, Cab45 has a fundamental role in sorting of select cargoes in the Golgi, but we provide new clues to a novel mechanism for binding CXCR4, which was able to significantly enhance tumor angiogenesis ability and invasive behavior." (PMID 33953165, 2021). "Additionally, in vivo tumor accumulation of T22-empowered NPs is efficiently inhibited by the CXCR4 antagonist AMD3100." (PMID 34208189, 2021). "MDSCs also express CXCR4 and can be recruited into tumor tissues by CXCL12." (PMID 34885241, 2021). "This suggests the possibility that CXCR4 could become a prognostic factor in a combined analysis with classical tumor markers such as carcinoembryonic antigen and C-reactive protein levels." (PMID 33579381, 2021). "An in vivo study confirmed the functional role of IL-33/CXCR4 in tumor initiation and metastasis." (PMID 34298657, 2021). "Notably, CXCR4 inhibition leads to an elimination of tumor cells by a rapid accumulation of cytotoxic CD8+ T cells." (PMID 34094963, 2021).